XCL1 (X-C motif chemokine ligand 1)
Description:
Chemotactic activity for lymphocytes but not for monocytes or neutrophils. In thymus, mediates medullary accumulation of thymic dendritic cells and contributes to regulatoy T cell development, playing a role in self-tolerance establishment.
Synonyms: LTN; SCYC1; LPTN; ATAC; SCM-1a; SCM-1; SCM1; SCM1A
Tractability: Antibody: its Gene Ontology location is reachable by antibodies, with high confidence; UniProt places it where antibodies can reach, with medium confidence; UniProt predicts a signal peptide or a membrane-spanning region.
Gene: Protein-coding gene on chromosome 1 (168,576,605 to 168,582,069, forward strand). Ensembl gene ENSG00000143184.
Subcellular location: Secreted
Pathways (Reactome):
Signal Transduction: Chemokine receptors bind chemokines; G alpha (q) signalling events
Gene Ontology:
Molecular function: chemokine activity; chemokine receptor binding; protein binding; protein homodimerization activity; CCR chemokine receptor binding
Biological process: cell-cell signaling; mature natural killer cell chemotaxis; negative regulation of CD4-positive, alpha-beta T cell proliferation; negative regulation of DNA-templated transcription; negative regulation of interleukin-2 production; negative regulation of T cell cytokine production; negative regulation of T-helper 1 cell activation; negative regulation of type II interferon production; positive regulation of CD8-positive, alpha-beta T cell proliferation; positive regulation of granzyme A production; positive regulation of granzyme B production; positive regulation of interleukin-10 production; positive regulation of natural killer cell chemotaxis; positive regulation of release of sequestered calcium ion into cytosol; positive regulation of T cell chemotaxis; positive regulation of T cell mediated cytotoxicity; positive regulation of transcription by RNA polymerase II; positive regulation of transforming growth factor beta production; regulation of inflammatory response; response to virus; antimicrobial humoral immune response mediated by antimicrobial peptide; cell chemotaxis; cellular response to interleukin-4; cellular response to transforming growth factor beta stimulus; chemokine-mediated signaling pathway; and 16 more
Cellular component: extracellular region
Genetic constraint (gnomAD): Loss-of-function variants: 6 observed, 7.87 expected, observed/expected ratio (o/e) 0.76, 90% interval 0.42 to 1.49. That is too few expected variants to judge how well the gene tolerates losing a copy. Missense variants: 122 observed, 126.49 expected, observed/expected ratio (o/e) 0.96, 90% interval 0.83 to 1.12. Synonymous variants: 48 observed, 52.32 expected, observed/expected ratio (o/e) 0.92, 90% interval 0.73 to 1.17.
Homologues: Orthologues: macaque XCL1 (91% identical), pig XCL1 (68% identical), mouse Xcl1 (61% identical), rat Xcl1 (55% identical), zebrafish cxcl32b.1 (28% identical). Paralogues in human: XCL2 (98% identical), CCL8 (29% identical), CCL7 (27% identical), CX3CL1 (26% identical), CCL26 (25% identical), CCL4 (25% identical), CCL11 (25% identical), CCL2 (25% identical), CCL13 (24% identical), CCL23 (24% identical), CCL3L3 (24% identical), CCL15 (23% identical), and 14 more.
Diseases named in the same sentence as XCL1 in open-access papers:
XCL1 is named in the same sentence as 92 diseases in open-access papers, as found by Europe PMC text mining. Sharing a sentence is not in itself a finding about the gene and the disease. The quoted sentences say what the papers report.
melanoma (19 papers, 2018 to 2025). A malignant, usually aggressive tumor composed of atypical, neoplastic melanocytes. "In a melanoma mouse model, the XCL1 and CCL5 produced by NK cells recruited Batf3 DCs to the tumor microenvironment." (PMID 38928238, 2024). "A fusion protein made of an antigen peptide presented with MHC class I and XCL1 plus an immune adjuvant contributed to reducing tumor growth in a mouse melanoma model in combination with an anti-PD-1 blockade." (PMID 38928238, 2024). "An XCL1 fusion peptide improved tumor rejection in a mouse B16 model of melanoma via recruitment of XCR1+ dendritic cells to the tumor." (PMID 38026637, 2023). "Recent studies of melanoma model mice and the TCGA melanoma dataset have shown that infiltration of cDC1 in the tumor is induced by XCL1, CCL5, or FMS-like tyrosine kinase 3 ligand (FLT3LG), which are produced by the NK cells infiltrated in the tumor." (PMID 37046775, 2023). "Certain types of melanoma or colon carcinoma tumors engineered to express high amount of XCL1 harbored a higher cDC1 infiltration and were rejected faster or grew more slowly in WT but not in Batf3−/− mice, as compared to control tumors." (PMID 30809220, 2019). "In view of the potent antitumor activity of Xcl1 fusion proteins observed in the EG7 tumor model, we assessed the tumor protective immunity of the Xcl1-mediated tumor vaccine in the less immunogenic B16-OVA melanoma tumor model." (PMID 30863405, 2019). "The role of NK cell-derived CCL5 and XCL1 in the recruitment of conventional type 1 dendritic cells (cDC1) leading to the anti-tumor CD8+ T cell response is identified in multiple subcutaneous tumor models including melanoma." (PMID 36733396, 2022). "Böttcher and colleagues analyzed The Cancer Genome Atlas data and found that a cDC1 signature was positively correlated with an XCL1/XCL2 and CCL5 chemokine signature and an NK-cell signature in breast cancer, melanoma, and lung adenocarcinoma." (PMID 39777457, 2025). "In this study, two populations of NK cells were identified: NKCyto (which compared with NK cells from OT metastatic melanoma lesions from NRs, expressing GNLY, CXC3R1, and FCGR3A) and NKRest (expressing XCL1 and XCL2)." (PMID 40530504, 2025). "The laser-assisted intradermal delivery of a tumor-specific tumor antigen combined with XCL1 resulted in the enhanced priming of CD8+ and CD4+ effector T cells by dermal DCs and better tumor control in a melanoma mouse model." (PMID 38928238, 2024). "Of relevance, we have previously observed that delivery of Xcl1-OVA fusion protein via laserporation of the skin induce cytotoxic T cell responses and reduce tumor growth in a B16 melanoma model." (PMID 30755656, 2019). "Similar to the analyses of cDC1 and NK cell gene signatures, we observed a positive correlation with survival when we ranked melanoma, HNSC and TNBC patients according to expression of CCL5, XCL1, and XCL2." (PMID 29429633, 2018). "Another mechanism of evasion of innate immunity by melanoma is tumor-intrinsic elevated COX activity leading to PGE2 production and downstream inhibition of NK cell, cDC1 and CTL infiltration, by disrupting the XCL1/XCR1 and CCL5/CCR5 chemotactic axes." (PMID 30809220, 2019). "Indeed, therapeutic vaccination with the Xcl1-(OVA SLP)-Fc fusion proteins was able to induce complete tumor regression in the EG7.OVA model and a delayed tumor growth in the more stringent B16.OVA melanoma model." (PMID 30863405, 2019).
breast carcinoma (7 papers, 2020 to 2025). "Further analysis in the breast cancer tissue microarrays revealed a positive correlation of cDC1 (XCR1+DCs) with XCL1-producing γδ T cells." (PMID 39209451, 2024). "In this study, we studied the effect of XCL1 on breast cancer cell migration and further elucidated the intracellular signaling pathway mediating the biological activity of the XCL1–XCR1 axis." (PMID 33374849, 2020). "We found that XCL1 promoted MDA-MB-231 breast cancer cell migration in a concentration-dependent manner." (PMID 33374849, 2020). "To obtain extended knowledge of XCL1 promoting breast cancer cell migration, we investigated the effect of XCL1 on the other breast cancer cell line using SK-BR-3 cells." (PMID 33374849, 2020). "Moreover, IL-38 negatively correlated with cDC1, XCL1-producing γδ T cells, T-cell infiltrates and survival in patients with mammary carcinoma." (PMID 39209451, 2024). "To explore whether the pro-migratory effect of XCL1 is specific for MDA-MB-231 cells or also applicable to the other type of breast cancer cells, we investigated the effects of XCL1 on cell migration and intracellular signaling in SK-BR-3 cells." (PMID 33374849, 2020). "It is possible that the involvement of MMP-2 and -9 in XCL1-induced breast cancer cell migration may be dependent on cell type." (PMID 33374849, 2020). "Therefore, to elucidate the intracellular signaling pathway that mediates XCL1-induced breast cancer cell migration, the effects of the XCL1–XCR1 axis on EMT markers, ERK1/2 activation, and HIF-1α expression were also examined in MDA-MB-231 and SK-BR-3 cells in this study." (PMID 33374849, 2020). "Therefore, the activation of ERK/HIF-1α/EMT signaling by XCL1 may specifically mediate the migration of breast cancer cells, including MDA-MB-231 and SK-BR-3 cells." (PMID 33374849, 2020). "Collectively, our results demonstrate that activation of the ERK/HIF-1α/EMT pathway is involved in the XCL1-induced migration of both MDA-MB-231 and SK-BR-3 breast cancer cells." (PMID 33374849, 2020). "X-C Motif chemokine Ligand 1 (XCL1) enhanced expression of HIF-1α and phosphorylation of extracellular signal-regulated kinase (ERK) 1/2, which induces EMT and imposes migration of breast cancer cells." (PMID 36226050, 2022). "Moreover, XCL1 accentuated HIF-1α accumulation and ERK1/2 phosphorylation in this breast cancer cells." (PMID 33374849, 2020).
influenza (6 papers, 2015 to 2023). An acute viral infection of the respiratory tract, occurring in isolated cases, in epidemics, or in pandemics; it is caused by serologically different strains of viruses (influenzaviruses) designated A, B, and C, has a 3-day incubation period, and usually lasts for 3 to 10 days. "Our observations indicate that immunization with Xcl1-HA induced stronger cellular and antibody responses when delivered by i.d. injection, which resulted in better protection against influenza infection." (PMID 30755656, 2019). "Here, we have used a murine influenza model to show that immunization with a fusion vaccine containing Xcl1(Δ1) resulted in improved antibody responses that provided better protection against infection." (PMID 31156636, 2019). "Here we evaluated in pigs the immunogenicity of bivalent protein structures made of XCL1 fused to the external portion of the influenza virus M2 proton pump, which is conserved through strains and a candidate for universal influenza vaccines." (PMID 28794452, 2017). "Depletion of Xcl1–HA-induced CD8+ T cells before viral challenge also confirmed that these cells played a central role in mediating protection against influenza." (PMID 26257735, 2015). "Consequently, Xcl1-HA induced superior protection against influenza infection compared to Ccl3-HA after i.d. immunization." (PMID 30755656, 2019). "Similar targeting approaches have been evaluated for influenza antigens, where the targeted delivery with chemokines such as CCL3 or XCL1, or the TLR ligand flagellin, have resulted in enhanced immunogenicity and protection against influenza." (PMID 26257735, 2015).
rheumatoid arthritis (5 papers, 2014 to 2024). A chronic, systemic autoimmune disorder characterized by inflammation in the synovial membranes and articular surfaces. "The pivotal role of XCL1 in activation of osteoclasts and osteoblasts highlights it as a therapeutic target for aseptic loosening and other diseases associated with bone destruction such as rheumatoid arthritis, Paget's disease, cancer bone metastases, and osteoporosis." (PMID 32849609, 2020). "In patients with rheumatoid arthritis, XCL1 manifests itself in the synovium, while XCR1 is a characteristic feature of infiltrating mononuclear and synovial cells." (PMID 38887195, 2024). "Nonetheless, there is a growing evidence suggesting the involvement of XCL1 in the development of arthritis and progressive bone degradation in rheumatoid arthritis." (PMID 32849609, 2020). "Of clinical interest, lymphotactin (XCL-1) is secreted along with other chemokines by aged CD4+ and CD8+ T cells and is thought to participate in T cell chemokine-dependent diseases of aging like rheumatoid arthritis and atherosclerosis." (PMID 32185730, 2020). "Xcr1 is the receptor for Xcl1 and Xcl2, which were not part of our microarray, but it is known that Xcrl also plays a role in rheumatoid arthritis and in the recruitment of cells to arthritic joints." (PMID 24967215, 2014). "In line with this view, XCL1 has been detected in synovial fluid, and XCR1 have been detected in the infiltrated mononuclear cells and synoviocytes within synovial tissues of rheumatoid arthritis patients." (PMID 32849609, 2020).
virus infection (5 papers, 2020 to 2025). "Among these genes, XCL1 and CXCL13 are chemokines that inhibit the apoptosis of immune cells during viral infection and play an important part in inflammatory response and immune regulation." (PMID 39682511, 2024). "On the other hand, HCV-associated cNK cells showed a pro-inflammatory profile, with high expression of the chemoattractants CCL3, CCL4, and XCL1, and the ligand TNFSF9 (CD137L), a costimulatory signal that can induce CD8+ T cells response against viral infection." (PMID 37063898, 2023). "We also observed a population of naïve CD4 T cells (denoted ‘Xcl1+ naïve’) expressing Lef1 and Sell genes along with Xcl1, which is a ligand of XCR1 (or G protein-coupled receptor 5, GPR5), with increased expression on NK and CD8+ T cells during virus infection." (PMID 40096073, 2025).
Obesity (4 papers, 2017 to 2025). Accumulation of substantial excess body fat. "While we observed fewer intestinal CD8+ T cells in obesity, previous publications demonstrated that these cells up‐regulate Xcl1 expression upon HFHSD." (PMID 41164009, 2025). "The specific role and systemic regulation of XCL1 in obesity is not fully understood; however, its specific expression in regions of fat deposition suggests a complex link to obesity." (PMID 39334887, 2024). "We speculate that exposure time to fatty acids may be a significant factor in the development of obesity and that elevated XCL1 production may be attributed to systemic coordination in an obese state." (PMID 29141038, 2017). "This review provides an in-depth analysis of specific chemokines involved in the development of obesity, including C-C motif chemokine ligand 2 (CCL2), CCL3, CCL5, CCL7, C-X-C motif chemokine ligand 8 (CXCL8), CXCL9, CXCL10, CXCL14, and XCL1 (lymphotactin)." (PMID 39334887, 2024). "In conclusion, a combination of upregulated obesity-related CVRPs (ANGPT1, IL, 1Ra, XCL1) and downregulated cardioprotective proteins (sRAGE, BMP6, Mn-SOD, GDF2) in PCOS may contribute to the increased risk of CVDs in overweight women with PCOS." (PMID 39858399, 2024).
squamous cell carcinoma (4 papers, 2020 to 2025). A carcinoma arising from squamous epithelial cells. "Site-specific sortase-mediated transpeptidation was performed to conjugate XCL1(CC3) to an analog of the HLA-A*02:01 epitope of the cancer testis antigen New York Esophageal Squamous Cell Carcinoma-1 (NY-ESO-1)." (PMID 35428705, 2022). "Of note, XCL1 was predominantly expressed in cancer cells showing adenocarcinoma morphology and dysplastic cells in the submucosa glands, while CD160 could be expressed in both squamous carcinoma and adenocarcinoma cells as well as in the proliferative and dysplastic cells of the submucosa glands." (PMID 39419971, 2024).
colon cancer (3 papers, 2020 to 2022). "Furthermore, the effects of the IRGs on colon cancer development remain unclear, although cancer progression has been linked to CD1B, XCL1, PLCG1, NGF, and OXTR." (PMID 32508884, 2020).
lung carcinoma (3 papers, 2024 to 2025). "Next, we evaluated the therapeutic effect of the XCL1-MS vaccine using a previously laboratory-established lung cancer model." (PMID 38339158, 2024). "Lung cancer cells express specific chemokines (such as CXCL12/14/16, CCL7/22, CX3CL1, and XCL1) and their corresponding receptors." (PMID 39512767, 2024).
neuroblastoma (3 papers, 2013 to 2021). Neuroblastoma (NB) is the most common solid, extracranial childhood tumor. "In addition, an immune vaccine modified with interleukin (IL2)‐XCL1 showed an obvious anti‐neuroblastoma effect." (PMID 33377624, 2021). "Two phase I clinical trials (NCT00062855 and NCT01713439) studied the safety and dosage of an injection of neuroblastoma cancer cells that were genetically engineered to express XCL1 and IL-2, with the first using autologous cancer cells and the second using the allogenic SJNB-JF-IL2/Lptn cell line." (PMID 32075343, 2020). "Additionally, a Phase I-II study is open for pediatric patients with advanced neuroblastoma using repeated immunization with gene-modified, IL-2/XCL1-secreting neuroblastoma tumor cell vaccines." (PMID 24967094, 2013).
atherosclerosis (2 papers, 2022 to 2025). A disease characterized by the build-up of fatty material and calcium deposition in the arterial wall resulting in partial or complete occlusion of the arterial lumen. "Collectively, these data suggest that Xcl1 promotes atherosclerosis by recruiting Xcr1+ cDC1 cells, and facilitating CD8+ T cell accumulation in lesions." (PMID 40934103, 2025). "Our results reveal crucial roles of cDC1 in atherosclerosis progression and provide insights into the development of immunotherapies by targeting cDC1 through Xcl1." (PMID 40934103, 2025). "After being fed with a HFD for 19 weeks, both Xcl1–/– Apoe–/– and Apoe–/– mice were sacrificed to assess the severity of atherosclerosis." (PMID 40934103, 2025). "In summary, our findings identify Xcl1 as a potential therapeutic target for atherosclerosis therapy, though its cellular origins and regulation of lesional Xcr1+ cDC1 and T cells dynamics require further studies." (PMID 40934103, 2025). "Our work paves the way to discover novel solutions for the treatment of atherosclerosis by targeting Xcl1 and Xcr1+ cDC1 cells." (PMID 40934103, 2025). "Most importantly, we have successfully demonstrated that targeting the chemokine Xcl1, the ligand of Xcr1, can effectively inhibit atherosclerosis." (PMID 40934103, 2025). "We identify two novel genes TCF7 and XCL1 derived from public single-cell-sequencing database of patients with atherosclerosis." (PMID 35792753, 2022). "As Xcr1 is the sole receptor for Xcl1, and Xcl1 selectively attracts Xcr1+ cDC1 cells in both mice and humans, we performed Xcl1 knockout on the background of Apoe–/– mice and assessed the impact on atherosclerosis development." (PMID 40934103, 2025). "We found that the Xcl1-Xcr1 axis plays a crucial role in the progression of atherosclerosis." (PMID 40934103, 2025). "To elucidate the causal relationship between Xcl1 and Xcr1+ cDC1 in the development of atherosclerosis, and more importantly, to experimentally verify Xcl1 as a potential therapeutic target for atherosclerosis treatment, we established the Xcl1 and Apoe double knockout mice." (PMID 40934103, 2025). "Studies on the role of TCF7 and XCL1 genes in atherosclerosis have not been widely reported, but these genes are highly expressed in immune cells of patients and mice with atherosclerosis, which may become potential therapeutic targets." (PMID 35792753, 2022).
brain injury (2 papers, 2023 to 2024). Acute and chronic (see also brain INJURIES, CHRONIC) injuries to the brain, including the cerebral hemispheres, CEREBELLUM, and brain STEM. "It has been found that XCL-1 expression levels were significantly reduced in the cerebrospinal fluid of subjects with post-traumatic brain injury." (PMID 39206161, 2024). "XCL1 is produced by subsets of T lymphocytes and NK cells during inflammation and is considered one of the triggers of secondary injury in traumatic brain injury." (PMID 37191423, 2023).